MLXIPL (MLX interacting protein like)
Description:
Glucose-responsive transcription activator that regulates fatty acid synthesis and glycolysis. Key determinant of systemic insulin sensitivity and glucose homeostasis. Important for the expression of fatty acid synthetic enzymes, including PC/Pcx, APOC4/Acl, ACACA/Acc1 and FASN/Fas (By similarity). Important for glucose-induced expression of L-type pyruvate kinase/PKLR (By similarity). Binds to the canonical and non-canonical E box DNA sequences 5'-CACGTG-3' and 5'-CACGCG-3' (By similarity). May also act as a transcriptional repressor (By similarity).
Synonyms: ChREBP; bHLHd14; WS-bHLH; MIO; WBSCR14; MONDOB
Tractability: Small molecule: a structure with a bound ligand is known.
Safety:
Unwanted effects reported when the protein is acted on. In parentheses: how it was acted on, where the effect was seen, and who reports it.
Increased, Liver Steatosis (activation; source: AOP-Wiki)
N/A, Liver Steatosis (activation; source: AOP-Wiki)
Gene: Protein-coding gene on chromosome 7 (73,593,194 to 73,624,568, reverse strand). Ensembl gene ENSG00000009950.
Subcellular location: Cytoplasm; Nucleus
Subcellular location (Human Protein Atlas): Nucleoplasm
Pathways (Reactome):
Metabolism: AMPK inhibits chREBP transcriptional activation activity; ChREBP activates metabolic gene expression; PKA-mediated phosphorylation of key metabolic factors; PP2A-mediated dephosphorylation of key metabolic factors
Gene Ontology:
Molecular function: DNA-binding transcription activator activity; DNA-binding transcription factor binding; protein heterodimerization activity; protein homodimerization activity; RNA polymerase II-specific DNA-binding transcription factor binding; carbohydrate response element binding; DNA binding; DNA-binding transcription factor activity; DNA-binding transcription factor activity, RNA polymerase II-specific; RNA polymerase II cis-regulatory region sequence-specific DNA binding; DNA-binding transcription activator activity, RNA polymerase II-specific; DNA-binding transcription repressor activity, RNA polymerase II-specific; protein dimerization activity
Biological process: lipid biosynthetic process; negative regulation of oxidative phosphorylation; positive regulation of cell population proliferation; positive regulation of glycolytic process; positive regulation of lipid biosynthetic process; anatomical structure morphogenesis; energy homeostasis; fatty acid homeostasis; glucose homeostasis; glucose mediated signaling pathway; negative regulation of DNA-templated transcription; positive regulation of DNA-templated transcription; positive regulation of fatty acid biosynthetic process; positive regulation of transcription by RNA polymerase II; regulation of DNA-templated transcription; regulation of transcription by RNA polymerase II; triglyceride homeostasis; negative regulation of transcription by RNA polymerase II; positive regulation of insulin secretion involved in cellular response to glucose stimulus; positive regulation of transcription from RNA polymerase II promoter by glucose
Cellular component: chromatin; nucleoplasm; cytoplasm; cytosol; nucleus; RNA polymerase II transcription regulator complex; transcription regulator complex
Genetic constraint (gnomAD): Loss-of-function variants: 48 observed, 69.06 expected, observed/expected ratio (o/e) 0.7, 90% interval 0.55 to 0.88. The upper end of that interval is the gene's LOEUF score, 0.88, which puts it in group 3 of 6, group 1 being the genes least tolerant of losing a copy. Missense variants: 1,031 observed, 999.4 expected, observed/expected ratio (o/e) 1.03, 90% interval 0.98 to 1.09. Synonymous variants: 455 observed, 405.49 expected, observed/expected ratio (o/e) 1.12, 90% interval 1.04 to 1.21.
Homologues: Orthologues: chimpanzee MLXIPL (99% identical), macaque MLXIPL (98% identical), dog MLXIPL (88% identical), pig MLXIPL (86% identical), rat AABR07035839.1 (84% identical), mouse Mlxipl (82% identical), guinea pig MLXIPL (81% identical), tropical clawed frog MLXIPL (44% identical), Drosophila melanogaster Mondo (29% identical), Caenorhabditis elegans mml-1 (25% identical), zebrafish mlxipl (15% identical). Paralogues in human: MLXIP (42% identical), MLX (10% identical), TFAP4 (9% identical).
Diseases named in the same sentence as MLXIPL in open-access papers:
MLXIPL is named in the same sentence as 106 diseases in open-access papers, as found by Europe PMC text mining. Sharing a sentence is not in itself a finding about the gene and the disease. The quoted sentences say what the papers report.
Hepatic steatosis (110 papers, 2010 to 2025). Steatosis is a term used to denote lipid accumulation within hepatocytes. "Collectively, these results indicate that MLXIPL expression is strongly associated with hepatic steatosis." (PMID 31809000, 2020). "H19 increased hepatic steatosis by upregulating mTORC1 and MLXIPL in hepatocytes, according to hepatocyte implantation experiments." (PMID 36552725, 2022). "Hepatocyte implantation studies further confirmed that H19 promoted hepatic steatosis by up‐regulating both mTORC1 and MLXIPL in hepatocytes." (PMID 31809000, 2020). "In vivo hepatocyte implantation studies further confirm that H19 promoted hepatic steatosis by up‐regulating both mTORC1 signalling axis and MLXIPL transcriptional network." (PMID 31809000, 2020). "Mechanistically, we showed that H19 promoted hepatic steatosis by up‐regulating MLXIPL/ChREBP and silencing Mlxipl diminished H19‐induced lipid accumulation in hepatocytes." (PMID 31809000, 2020). "We first confirmed that MLXIPL expression was significantly up‐regulated in OA‐induced hepatic steatosis both at mRNA and protein levels." (PMID 31809000, 2020). "Mechanistically, H19 was shown to promote hepatic steatosis by up‐regulating lipogenic transcription factor MLXIPL." (PMID 31809000, 2020). "By upregulating MLXIPL/ChREBP and silencing, Mlxipl reduced H19-induced hepatic steatosis." (PMID 36552725, 2022). "Control IgG of masses was shown.Collectively, these results strongly suggest that lncRNA H19 may promote hepatic steatosis by up‐regulating both mTORC1 signalling complex and MLXIPL transcriptional network in hepatocytes." (PMID 31809000, 2020). "Taken together, these results suggest that MLXIPL may be an important mediator of H19‐promoted hepatic steatosis." (PMID 31809000, 2020). "Among lipogenesis-related transcription factors, SREBP1 and NR1H3 (LXR) genes were elevated in liver tissues of hepatic steatosis patients, but MLXIPL (ChREBP) genes remained unchanged." (PMID 32332706, 2020). "Mechanistically, we found that H19 promoted hepatic steatosis by up‐regulating and the mTORC1 signalling axis (including active RAPTOR, mTOR, S6K SREBP and suppress LIPIN1) and MLXIPL transcriptional network in hepatocytes." (PMID 31809000, 2020). "The combination of Arazyme with ESLs significantly reduced hepatic steatosis by inhibiting SREBP-1- and MLXIPL-mediated fatty acid synthesis but did not change the plasma TG levels." (PMID 34357017, 2021).
Insulin resistance (87 papers, 2010 to 2026). Increased resistance towards insulin, that is, diminished effectiveness of insulin in reducing blood glucose levels. "Venn diagram analysis revealed that seven DEGs (CXCL8, MLXIPL, CREB3L1, EGR1, NOTCH3, ACTA2, and SERPINE1) were associated with both obesity and diabetes-associated pathways, including non-alcoholic fatty liver disease, insulin resistance, thermogenesis, and apelin signaling pathways." (PMID 38570815, 2024). "MLX-interacting protein-like (MLXIPL; also known as ChREBP) is reported to be involved in energy microenvironment homeostasis and insulin resistance." (PMID 31493764, 2019). "Both the candidate genes STX-1A and MLXIPL/ChREBP might be involved in the development of IGM and DM, accounting for β-cell dysfunction and insulin resistance, respectively." (PMID 29053727, 2017).
Obesity (55 papers, 2010 to 2025). Accumulation of substantial excess body fat. "The effect of MLXIPL Gln241His on liver disease was most pronounced among those at the highest risk of SLD, namely those with obesity, T2D mellitus, and carriers of PNPLA3 I148M." (PMID 38668731, 2024). "The association of MLXIPL Gln241His with SLD was more pronounced in subgroups with common SLD comorbidities and risk factors like T2D or obesity, as well as carriers of patatin-like phospholipase domain-containing protein 3 (PNPLA3) I148M." (PMID 38668731, 2024). "A whole-transcriptome study revealed differentially expressed target genes important in obesity and diabetes-related pathways such as MLXIPL, CREB3L1, EGR1, ACTA2, SERPINE1, NOTCH3, and CXCL8." (PMID 38570815, 2024).
Hyperglycemia (49 papers, 2012 to 2025). An increased concentration of glucose in the blood. "Furthermore, hyperglycemic cultures had elevated FASN and SREBF1 gene expression, whereas the expression of MLXIPL was unchanged by hyperglycemia as compared to normoglycemic cultures." (PMID 27312339, 2016).
steatosis (42 papers, 2013 to 2026). Increased lipid within the cytoplasm of cells. "Other steatosis-related genes except MLXIPL were found to be weakly downregulated in the high concentration, while the low concentration weakly upregulated these genes." (PMID 40295322, 2025). "More mechanistic studies are needed to better understand the role of MLXIPL Gln241His on lipid metabolism and steatosis development." (PMID 38668731, 2024). "H19 promotes steatosis and lipid accumulation by modulating several pathways, including the miR-130a/peroxisome proliferator-activated receptor gamma (PPARγ) axis, MLX-interacting protein-like (MLXIPL) expression, and mechanistic target of rapamycin complex 1 (mTORC1) signaling." (PMID 40392981, 2025).
diabetes (31 papers, 2010 to 2025). "Interestingly, one of the human homologs of MML-1, carbohydrate response element binding protein (ChREBP/MondoB/MLXIPL/WBSCR14), maps within a deleted region in Williams-Beuren syndrome patients, which among other symptoms causes metabolic dysfunction, silent diabetes, and premature aging." (PMID 37338980, 2023). "Genes such as KCNE2, DLL1, ACVR1C, RGS3, MLXIPL (MLX interacting protein like), PAG1, SLC2A10 and GRB14 play important role in type 2 diabetes mellitus progression." (PMID 33902539, 2021).
dyslipidemia (21 papers, 2015 to 2025). "The first is MLXIPL, a gene that is deleted in Williams-Beuren syndrome, a multisystem developmental disorder, and is associated with non-alcoholic fatty liver disease as well as metabolic syndrome." (PMID 38785970, 2024). "In a study of Chinese genetic variants in lipid parameters and dyslipidemia, HDL-C levels decreased from 1.38 mmol/L for individuals carrying three or fewer risk alleles to 1.14 mmol/L for individuals carrying all eight risk alleles (MLXIPL rs17145738, LPLrs326, LIPC rs1800588 and CETP rs3764261)." (PMID 28915626, 2017).
hepatocellular carcinoma (21 papers, 2016 to 2025). A malignant tumor that arises from hepatocytes. "Through triggering the expression of the PI3K regulatory subunit p85α, MLXIPL sustains the activity of the pro-oncogenic PI3K/AKT signaling pathway in hepatocellular cancer." (PMID 38698844, 2024). "Essentially, MLXIPL is responsible for the modulation of hepatic carcinoma." (PMID 38785970, 2024). "MLXIPL mRNA showed positive connections with glycolytic and lipogenic genes in chromatin immunoprecipitation analysis of human hepatocellular carcinoma (HCC) and breast cancer." (PMID 38933330, 2024).
non-alcoholic fatty liver disease (12 papers, 2014 to 2025). "The most significant is that CASP14 and MLXIPL participate in the metabolism of nonalcoholic fatty liver disease (P = 0.0006)." (PMID 40029616, 2025).
hypertriglyceridemia (11 papers, 2012 to 2025). A laboratory test result indicating elevated triglyceride concentration in the blood. "The MLXIPL rs3812316 was associated with lower baseline TAG (p < 0.0001) and lower hypertriglyceridemia (odds ratio, 0.73 in G-carriers vs. CC homozygotes)." (PMID 35387194, 2022).
breast carcinoma (7 papers, 2013 to 2024). "Furthermore, increased MLXIPL staining has been observed in breast cancer, exhibiting a clear positive correlation with malignant progression." (PMID 38698844, 2024).
colon cancer (7 papers, 2016 to 2024). "Knockdown of MLXIPL impedes colon cancer cell glycolytic and lipogenic pathways, thereby inhibiting cell proliferation and blocking the cell cycle." (PMID 36809979, 2023).
hyperlipidemia (7 papers, 2013 to 2024). "MLXIPL might, therefore, be a potential pharmacological target for the treatment of SLD and hyperlipidemia, notably for patients at risk." (PMID 38668731, 2024).
liver disease (6 papers, 2021 to 2025). "Homozygotes for MLXIPL Gln241His had a significantly greater risk of a SLD diagnosis; heterozygous carriers of MLXIPL Gln241His had a higher risk of liver disease (ICD10 code K76) compared to controls (p-value=0.038) that remained significant after multivariate analysis." (PMID 38668731, 2024). "For example, specific alleles in variants in/near APOE, LIPC, MLXIPL, and TM6SF2 promote liver disease while resulting in a favorable serum lipid profile of decreased TG/LDL or increased HDL, suggesting they may cause liver disease by sequestering lipids/metabolites in the liver." (PMID 33547301, 2021).
Williams-Beuren syndrome (6 papers, 2014 to 2024). "MLXIPL expression is significantly decreased in mice whose spermatogenesis and fertility are disturbed, and mutations in this gene are associated with Williams syndrome, characterized by cryptorchidism in male patients." (PMID 34702182, 2021). "Notably, MLXIPL is one of the 26–28 genes deleted in Williams syndrome, the result of a deletion of contiguous genes on chromosome 7q11.23." (PMID 36530175, 2022).
gout (5 papers, 2014 to 2025). A condition characterized by painful swelling of the joints, which is caused by deposition of urate crystals. "Between the individual alcoholic beverage types, beer intake was observed to have the most significant interaction with ADH1B rs1229984 for association with serum urate level, hyperuricaemia, and gout and with MLXIPL rs6460047 for association with serum urate level among all participants." (PMID 38331848, 2024). "Among the other genes significantly associated with gout, seven loci have also been previously identified in GWAS, including those in the genes SLC17A1, GCKR, SLC22A11, ADH1B, MLXIPL, RREB1 and SLC16A9." (PMID 41075270, 2025). "In this large study of European participants, novel interactions with alcohol consumption were identified at ADH1B and MLXIPL for association with serum urate level and at ADH1B for association with hyperuricaemia and gout." (PMID 38331848, 2024). "In summary, this study has identified novel interactions with alcohol consumption at ADH1B and MLXIPL for association with serum urate level and at ADH1B for association with hyperuricaemia and gout among individuals of European ethnicity." (PMID 38331848, 2024). "For example, there are loci associated with control of serum urate levels that contain genes that are also associated with serum Tg levels (GCKR, MLXIPL, A1CF) and gout." (PMID 25432151, 2014). "The urate-increasing GCKR and ABCG2 alleles were associated with gout (multivariate adjusted p < 5 × 10−8 for both), but the urate-increasing MLXIPL and CYP1A2 alleles were not." (PMID 29976226, 2018). "Neither MLXIPL nor CYP1A2 were associated with gout, with multivariate adjusted OR 1.24 (95% CI 0.95–1.61, P = 0.11) and 1.16 (95% CI 0.96–1.40, P = 0.12), respectively." (PMID 29976226, 2018). "In the genotype-stratified association analyses, ADH1B and MLXIPL were associated with serum urate level and ADH1B was associated with hyperuricaemia and gout among consumers of alcohol but not non-consumers." (PMID 38331848, 2024).
coronary artery disease (4 papers, 2016 to 2025). "MLXIPL (also known as ChREBP) is associated with elevated plasma triglyceride levels, increased concentrations of liver enzymes, and a higher risk of coronary artery disease." (PMID 41075270, 2025). "In humans, variants in the ChREBP gene, MLXIPL, have been associated with elevated plasma triglyceride levels and coronary artery disease, supporting a role for ChREBP in metabolic health." (PMID 27992582, 2016).
irritable bowel syndrome (4 papers, 2018 to 2025). Irritable bowel syndrome (IBS) is a chronic functional condition of the lower gastrointestinal (GI) tract characterized by abdominal pain or discomfort and disordered bowel habit (diarrhea, constipation, or fluctuation between the two). "While this may be a potential therapeutic target for fat distribution, mice deficient in MLXIPL/ChREBP do not tolerate fructose in their diet and develop severe diarrhea and irritable bowel syndrome." (PMID 40912257, 2025).
hyperuricaemia (2 papers, 2024). "First, variants in MLXIPL and ANO5 were found to cause extreme quantitative traits in hyperuricemia and limb-girdle muscular dystrophy, respectively." (PMID 38584274, 2024).
metastatic tumors (2 papers, 2016 to 2017). "Genetic alterations in metabolic genes associated with metastatic progression analyzed, revealed that genes involved in cellular fatty acid uptake (CAV1, CD36) and de novo lipogenesis (PPARA, PPARD, MLXIPL) were specifically amplified at higher frequencies in metastatic tumors." (PMID 28798698, 2017). "However, genes involved in cellular FA uptake (CAV1, CD36) and de novo lipogenesis (PPARA, PPARD, MLXIPL) were specifically amplified at higher frequencies in metastatic tumors." (PMID 26725848, 2016). "However, 6 genes were amplified at significantly higher frequencies in metastatic tumors: SCO2 (p = 1.1 × 10−9), MLXIPL (p = 2.1 × 10−4), PPARA (p = 1.2 × 10−10), PPARD (p = 4 × 10−15), CAV1 (p = 3.4 × 10−4) and CD36 (p = 3.5 × 10−4)." (PMID 26725848, 2016).
acinar adenocarcinoma (1 paper, 2024). "In the high MLXIPL group, we observed a decreased acinar adenocarcinoma ratio and an increased number of nodes." (PMID 38698844, 2024).
gastric tumor (1 paper, 2024). "However, in gastric tumor, MLXIPL inhibits proliferation and promotes apoptosis via targeting the cyclin D1-Rb-E2F1 pathway." (PMID 38698844, 2024).
prostate acinar adenocarcinoma (1 paper, 2024). "The density of CD8+ T cells and expression of MLXIPL was lower in prostate acinar adenocarcinoma compared to other histopathological subtypes of PCa." (PMID 38698844, 2024).